LRRC36 (leucine rich repeat containing 36)
Synonyms: RORBP70; FLJ11004; XLHSRF2
Tractability: PROTAC: ubiquitination databases record sites on it.
Gene: Protein-coding gene on chromosome 16 (67,326,798 to 67,385,204, forward strand). Ensembl gene ENSG00000159708.
Subcellular location (Human Protein Atlas): Mitochondria; Vesicles
Gene Ontology:
Molecular function: protein binding
Genetic constraint (gnomAD): Loss-of-function variants: 41 observed, 59.06 expected, observed/expected ratio (o/e) 0.69, 90% interval 0.54 to 0.9. The upper end of that interval is the gene's LOEUF score, 0.9, which puts it in group 3 of 6, group 1 being the genes least tolerant of losing a copy. Missense variants: 697 observed, 817.27 expected, observed/expected ratio (o/e) 0.85, 90% interval 0.8 to 0.91. Synonymous variants: 305 observed, 331.47 expected, observed/expected ratio (o/e) 0.92, 90% interval 0.84 to 1.01.
Homologues: Orthologues: chimpanzee LRRC36 (99% identical), macaque LRRC36 (97% identical), dog LRRC36 (88% identical), pig LRRC36 (87% identical), rabbit LRRC36 (86% identical), guinea pig LRRC36 (84% identical), mouse Lrrc36 (81% identical), rat Lrrc36 (81% identical), tropical clawed frog lrrc36 (23% identical). Paralogues in human: CEP72 (22% identical).
Diseases named in the same sentence as LRRC36 in open-access papers:
LRRC36 is named in the same sentence as 2 diseases in open-access papers, as found by Europe PMC text mining. Sharing a sentence is not in itself a finding about the gene and the disease. The quoted sentences say what the papers report.
Azoospermia (1 paper, 2023). Absence of any measurable level of sperm,whereby spermatozoa cannot be observed even after centrifugation of the semen pellet. "Although KCTD19 and LRRC36 genes are mainly expressed in the testis and could not be directly associated with POI phenotype, KCTD19 knockout mice produced spermatocytes that failed to complete meiosis, leading to azoospermia, indicating its role in meiosis and, putatively, gametogenesis in general." (PMID 37202802, 2023).
LRRC36 also shares sentences with these, for which no sentence is quoted: schizophrenia (1 paper).